NFATC3 (nuclear factor of activated T cells 3)
Description:
Acts as a regulator of transcriptional activation. Binds to the TNFSF11/RANKL promoter region and promotes TNFSF11 transcription (By similarity). Binding to the TNFSF11 promoter region is increased by high levels of Ca(2+) which induce NFATC3 expression and may lead to regulation of TNFSF11 expression in osteoblasts (By similarity). Plays a role in promoting mesenteric arterial wall remodeling in response to the intermittent hypoxia-induced increase in EDN1 and ROCK signaling (By similarity). As a result NFATC3 colocalizes with F-actin filaments, translocates to the nucleus and promotes transcription of the smooth muscle hypertrophy and differentiation marker ACTA2 (By similarity). Promotes lipopolysaccharide-induced apoptosis and hypertrophy in cardiomyocytes (By similarity). Following JAK/STAT signaling activation and as part of a complex with NFATC4 and STAT3, binds to the alpha-beta E4 promoter region of CRYAB and activates transcription in cardiomyocytes (By similarity). In conjunction with NFATC4, involved in embryonic heart development via maintenance of cardiomyocyte survival, proliferation and differentiation (By similarity). Plays a role in the inducible expression of cytokine genes in T-cells, especially in the induction of the IL-2. Required for thymocyte maturation during DN3 to DN4 transition and during positive selection (By similarity). Positively regulates macrophage-derived polymicrobial clearance, via binding to the promoter region and promoting transcription of NOS2 resulting in subsequent generation of nitric oxide (By similarity). Involved in Ca(2+)-mediated transcriptional responses upon Ca(2+) influx via ORAI1 CRAC channels.
Synonyms: NF-AT4c; NFAT4; NFATX; n339260
Tractability: Small molecule: a structure with a bound ligand is known. PROTAC: UniProt records ubiquitination sites on it; ubiquitination databases record sites on it; its protein half-life has been measured.
Gene: Protein-coding gene on chromosome 16 (68,084,751 to 68,229,259, forward strand). Ensembl gene ENSG00000072736.
Subcellular location: Cytoplasm; Nucleus
Subcellular location (Human Protein Atlas): Cytosol; Nucleoplasm
Pathways (Reactome):
Immune System: CLEC7A (Dectin-1) induces NFAT activation; Calcineurin activates NFAT; FCERI mediated Ca+2 mobilization
Gene Ontology:
Molecular function: DNA-binding transcription activator activity, RNA polymerase II-specific; DNA-binding transcription repressor activity, RNA polymerase II-specific; protein binding; RNA polymerase II cis-regulatory region sequence-specific DNA binding; sequence-specific double-stranded DNA binding; DNA-binding transcription factor activity, RNA polymerase II-specific; DNA binding; DNA-binding transcription factor activity
Biological process: negative regulation of miRNA transcription; negative regulation of vascular associated smooth muscle cell differentiation; positive regulation of transcription by RNA polymerase II; calcineurin-NFAT signaling cascade; DN4 thymocyte differentiation; inflammatory response; positive regulation of artery morphogenesis; positive regulation of nitric oxide biosynthetic process; positive thymic T cell selection; regulation of transcription by RNA polymerase II; negative regulation of transcription by RNA polymerase II; regulation of DNA-templated transcription
Cellular component: cytoplasm; cytosol; nucleoplasm; nucleus; chromatin; transcription regulator complex
Genetic constraint (gnomAD): Loss-of-function variants: 43 observed, 90.69 expected, observed/expected ratio (o/e) 0.47, 90% interval 0.37 to 0.61. The upper end of that interval is the gene's LOEUF score, 0.61, which puts it in group 2 of 6, group 1 being the genes least tolerant of losing a copy. Missense variants: 1,218 observed, 1,294 expected, observed/expected ratio (o/e) 0.94, 90% interval 0.9 to 0.99. Synonymous variants: 502 observed, 476.23 expected, observed/expected ratio (o/e) 1.05, 90% interval 0.98 to 1.13.
Homologues: Orthologues: chimpanzee NFATC3 (99% identical), macaque NFATC3 (98% identical), dog NFATC3 (93% identical), pig NFATC3 (93% identical), rabbit NFATC3 (91% identical), guinea pig NFATC3 (89% identical), mouse Nfatc3 (89% identical), rat Nfatc3 (88% identical), zebrafish nfatc3a (60% identical), tropical clawed frog nfatc3 (51% identical). Paralogues in human: NFATC4 (37% identical), NFATC1 (35% identical), NFATC2 (32% identical), NFAT5 (24% identical).
Diseases named in the same sentence as NFATC3 in open-access papers:
NFATC3 is named in the same sentence as 108 diseases in open-access papers, as found by Europe PMC text mining. Sharing a sentence is not in itself a finding about the gene and the disease. The quoted sentences say what the papers report.
cardiac hypertrophy (37 papers, 2010 to 2025). "The myocardial hypertrophy is associated with activation of the TRPC/CaN/NFATc3 axis in AH models with intact kidneys, which is confirmed in this study." (PMID 33924991, 2021). "Previous researches have implicated GATA-4 and NFATc3 as primary transcription factors in cardiac hypertrophy responses." (PMID 31480672, 2019). "Furthermore, it also suppressed the expression of fibrosis markers COL1A1, CTGF, and uPA and downregulated cardiac-hypertrophy-associated markers such as calcineurin, NFATC3, GATA4, pGATA4 and BNP." (PMID 35890118, 2022). "However, when β-catenin expression was suppressed using an inhibitor XAV 939, cardiac hypertrophy associated transcription factor NFATc3 and hypertrophy marker BNP were also downregulated." (PMID 31480672, 2019). "Given that Nfatc3 is the main transcription factor that mediates the signal transduction of cardiac hypertrophy, this study confirms that the lncRNA Jpx participates in testosterone-induced cardiac hypertrophy through the miR-145-5p/Nfatc3 axis." (PMID 40874024, 2025). "NFATc3 facilitates upregulation of myocardin expression; in contrast, miR-9 acts to reduce myocardin expression, thereby modulating cardiac hypertrophy." (PMID 41226851, 2025). "Mechanistically, Jpx acts as a competing endogenous RNA (ceRNA) to regulate Nfatc3 (Nuclear factor of activated T cells 3) expression by binding miR-145-5p, subsequently promoting cardiac hypertrophy." (PMID 40874024, 2025). "Mechanistic analysis suggested that Jpx overexpression facilitates testosterone-induced cardiac hypertrophy by regulating the miR-145-5p/Nfatc3 axis, providing new insights for understanding the function of lncRNAs in the pathogenesis of cardiac hypertrophy." (PMID 40874024, 2025). "Overall, these results demonstrate that Nfatc3 is a target of miR-145-5p, and that Jpx acts as the competing endogenous RNA (ceRNA) of Nfatc3 by absorbing miR-145-5p in testosterone-induced cardiac hypertrophy." (PMID 40874024, 2025). "Among the predicted potential targets of miR-145-5p, we focused on Nfatc3, because it is the main effector molecule downstream of calcineurin (CaN) in the heart, which is essential for the development of cardiac hypertrophy." (PMID 40874024, 2025). "Future studies are needed to further elucidate the mechanisms by which lncRNAs regulate androgen-induced cardiac hypertrophy, validating the Jpx/miR-145-5p/Nfatc3 axis in primary cardiomyocytes and animal models to enhance its translational significance." (PMID 40874024, 2025). "Astragalus polysaccharide can also exert its anti-myocardial hypertrophy effect through inhibiting the activities of Ca2+ mediated calcineurin/nuclear factor of activated T-cells 3 (NFATC3) and calcineurin kinase II (CaMK-II)." (PMID 38444481, 2024). "Several studies have indicated that the CaN/NFATc3 pathway was intimately related to myocardial fibrosis in spontaneously hypertensive rats and angiotensin II induced cardiac hypertrophy." (PMID 37735624, 2023). "For instance, Tan IIA alleviates cardiac hypertrophy via inhibiting calcineurin/NFATc3 or Cys-c/Wnt signaling." (PMID 35191812, 2022). "We observed no further alterations in NFATc2 at AB1–18 weeks, and a persistent decrease in NFATc3 mRNA throughout cardiac hypertrophy and dilatation." (PMID 39086965, 2022). "Activated calcineurin/NFATc3 signaling was established to transduce cardiac hypertrophy signaling in cardiomyocytes." (PMID 34684485, 2021). "According to our previous study, TRPV3 aggravates pathological myocardial hypertrophy through the calcineurin/NFATc3 pathway, promoting the extracellular Ca2+ flow and increases [Ca2+]i, and aggravates cardiac fibrosis through the TGF-β1 pathway." (PMID 33470394, 2021). "ISO-induced cardiac hypertrophy in rats increased the expression of calcineurin and phosphorylated NFATc3 in LV tissue." (PMID 34684485, 2021).
cardiac hypertrophy (continued). "The activated β-adrenergic signaling by ISO injection led to LV hypertrophy through calcineurin/NFATc3 pathway." (PMID 34684485, 2021). "Given that NFATc3 activates many downstream genes associated with cardiac hypertrophy, it would be worth investigating whether NFATc3/miR-153-3p axis is involved in the regulation of other proteins related to mitochondrial dynamics during the development of cardiac hypertrophy." (PMID 31903137, 2020). "In this study, we uncovered the link between the increased NFATc3 activity and aberrant mitochondrial fission in cardiac hypertrophy." (PMID 31903137, 2020). "Calcineurin activation hasa regulatory role during cardiac hypertrophy through NFATc3/GATA4 pathway." (PMID 31211784, 2019). "Previously, NFATc3 and GATA4 transgenic overexpression studies reveal its significant association in the development of myocardial hypertrophy." (PMID 31211784, 2019). "Taken together, our results supported this idea that calcineurin/NFATc3 pathway was involved in the cardiac hypertrophy induced by the activation of TRPV3." (PMID 30299584, 2018). "We found that TRPV3 activation promoted cardiac hypertrophy via Ca2+/CaMKII/calcineurin/NFATc3 pathway." (PMID 30299584, 2018). "In summary, our study established that TRPV3 was activated by hypertrophic stimulus, and intracellular calcium concentration was increased, which in turn activated calcineurin/NFATc3 pathway, and eventually led to cardiac hypertrophy." (PMID 30299584, 2018). "The up-regulation of miR-328 expression suppresses its target gene SERCA2a (ATPase Sarcoplasmic/Endoplasmic Reticulum Ca2+ Transporting 2) in cardiac myocytes to indirectly activate the calcineurin/NFATc3 signaling pathway, leading to cardiac hypertrophy." (PMID 28558735, 2017). "Transgenic animals that express a constitutively active mutant of calcineurin or NFATc3 undergo cardiac hypertrophy." (PMID 27977752, 2016). "Among the five members of NFAT family, NFATc3 is an essential downstream effector of calcineurin-regulated cardiac hypertrophy." (PMID 25767890, 2015). "GATA4 is a zinc finger, containing transcription factor that plays key roles in promoting heart growth and regulating cardiac hypertrophy, and is associated with multiple hypertrophic signaling pathways, such as ERK1/2, p38, Akt, and CnA/NFATc3." (PMID 25093027, 2014). "GSK3β is shown to inhibit cardiac hypertrophy by preventing the nuclear translocation of nuclear factor of activated T-cells (NFATc3) via the phosphorylation of NFATc3." (PMID 22043204, 2010). "BA decreased calcineurin and p-NFATc3 activation in ISO-induced cardiac hypertrophy." (PMID 34684485, 2021). "Through miRNA sponge technology, we demonstrated that inhibition of endogenous miR-30 in cardiomyocytes not only directly leads to pathological cardiac hypertrophy but also enhances the phosphatase activity of calcineurin and promotes nuclear translocation of NFATc3." (PMID 33848263, 2021). "According to these results, we hypothesized that miR-30 regulates cardiac hypertrophy in CKD via the calcineurin/NFATc3 pathway." (PMID 33848263, 2021). "Nuclear factor of activated T cells cytoplasmic 3 (NFATc3) is an indispensable component of Calcineurin-induced cardiac hypertrophy, and it can be dephosphorylated by calcineurin, thus translocating to the nucleus and exerting transcriptional regulatory functions." (PMID 33848263, 2021). "Thus, we concluded that calcineurin/NFATc3 connects miR-30 with cardiac hypertrophy, and miR-30 downregulation is essential for CKD-induced LVH." (PMID 33848263, 2021). "Above all, miR-30 suppression may result in cardiac hypertrophy via calcineurin/NFATc3 activation in LVH." (PMID 33848263, 2021). "NFATc3 is one of the central effectors of signaling pathways in cardiac hypertrophy." (PMID 31903137, 2020).
cardiac hypertrophy (continued). "Therefore, we also deduced the nuclear enrichment of cardiac hypertrophy associated transcription factors and noticed there was increased nuclear enrichment of GATA4 and NFATc3 with β-catenin upon Ang-II treatment in a dose-dependent assessment." (PMID 31480672, 2019). "However, several other studies have implicated the transcription factors NFATc3 and GATA4 in development of pathological cardiac hypertrophy." (PMID 31480672, 2019). "In addition, calcineurin/NFATc3 hypertrophic signalling pathway plays a pivotal role in cardiac hypertrophy." (PMID 30299584, 2018). "The results confirm that ISO induced cardiac-hypertrophy by elevating the levels of hypertrophy associated proteins, ANP and BNP and further by upregulating p-CaMKII, calcineurin, p-GATA4 and NFATc3 which was correlated with a significant enlargement of the H9c2 cardiomyoblast." (PMID 28863192, 2017). "This activation evokes a dephosphorylation of NFATc3 within the cytoplasm, which translocates to the nucleus, where it associates with transcription factor like GATA-4, to regulate the cardiac genes and develop cardiac hypertrophy." (PMID 27880816, 2016). "A potential role in cardiac hypertrophy has been shown for NFATc2, NFATc3, and NFATc4." (PMID 26617522, 2015). "NFATc3 is a transcription factor which activates several genes related to cardiac hypertrophy." (PMID 22043204, 2010). "● MiR-30 suppression may result in cardiac hypertrophy via calcineurin/NFATc3 activation in LVH." (PMID 38074330, 2023). "However, the involvement of NFATc3-dependent signaling in the regulation of mitochondrial dynamics during cardiac hypertrophy remains unknown." (PMID 31903137, 2020). "Also, treatment with either AT1 receptor blocker or tempol attenated STZ-induced cardiac hypertrophy and fibrosis by attenuating the inactivation of GSK3β and thus preventing the nuclear translocation of NFATc3, and also attenuated PKCβ2 and p38 MAPK signaling 28 days after STZ injection." (PMID 22043204, 2010). "The cardiac hypertrophy marker B-type natriuretic peptide (BNP), which is up-regulated by NFATc3, was up-regulated compared to the control group." (PMID 26496028, 2015). "Besides, Arsenic-induced cardiac hypertrophy is mediated by reducing the expression of AMPK and FoxO1, thereby increasing the expression of NFATc3." (PMID 34305607, 2021). "Interestingly, they observed that oleic acid (100 μM) reduced the expression of NFATc3 by activating AMPK and increasing the localization of FoxO, thereby helping to relieve cardiac hypertrophy induced by arsenic (1 μM) in H9c2 cells." (PMID 34305607, 2021). "Prophylactic resistance training attenuated most of these changes, except angiotensin II, fibrosis, heart rate and concentric remodeling of left ventricle, confirmed by the increased of NFATc3 and GATA-4, proteins involved in the pathologic cardiac hypertrophy pathway." (PMID 27880816, 2016). "Later it became clear that NFATc3 as well as c4, but not c2 are necessary for cardiac hypertrophy in multiple models." (PMID 26617522, 2015). "Unlike other prohypertrophic signaling pathways, the calcineurin/NFATc3 pathway participates in pathological, but not physiological, cardiac hypertrophy; thus, it may manifest more important significance in CKD-induced LVH." (PMID 33848263, 2021). "For example, the pharmacological NFATc3 inhibitor A-285222 protected from endothelial dysfunction in a murine diabetes model but does not block NFATc2 playing a central role in pathological myocardial hypertrophy." (PMID 34089101, 2021).
breast carcinoma (14 papers, 2011 to 2025). "For instance, TRPC5-mediated Ca2+ entry was reported to stimulate P-glycoprotein production in adriamycin-resistant MCF-7/ADM breast cancer cells via NFATc3." (PMID 39436410, 2025). "The lncRNA NRON can regulate osteoclastogenesis during orthodontic bone resorption, reduce atrial fibrosis by promoting NFATc3 phosphorylation, inhibit breast cancer development via regulating miR-302b/SRSF2 axis." (PMID 34861891, 2021). "Earlier evidence demonstrated that TRPC5 was up-regulated and induced P-gp overexpression by hyper-stimulating the Ca2+-dependent transcription factor, NFATc3 in chemoresistant MCF-7 breast cancer cells." (PMID 29324706, 2018). "Additionally, NFATC3, which is related to the Calcium signaling pathway, is involved in alcohol-induced breast cancer growth." (PMID 40452916, 2025). "Indeed, high expression of NFATC3, CBX6 and CNOT6L is associated with better survival in breast cancer patients." (PMID 37409119, 2023). "NFATC3 was widely associated with the progression and prognosis of multiple human cancers, such as colorectal cancer (CRC) 44, gastrointestinal cancer 45, human glioblastoma (hGB) 46, oral/oropharyngeal squamous cell carcinoma (OSCC) 47 and breast cancer." (PMID 33995646, 2021). "Additionally, it has been suggested that microRNA-320a (miR-320a), which acts as a tumor suppressor, could target and degrade TRPC5 and NFATC3 mRNAs, which are involved in breast cancer chemoresistance." (PMID 37755210, 2023). "In our study, the high correlation between CSNK1A1 and NFATC3 is associated with poor survival in the ER-negative group, which suggests that pharmacological inhibition of NFATC3 by targeting CSNK1A1 could be of therapeutic interest for breast cancer patients." (PMID 33450402, 2020). "Hesperidin effectively reduced tumour growth, which was accompanied by depressed vascular density and downregulation of VEGF, NFATc3, VEGF, and VEGFR2 in xenograft BALB/c mice model in vivo and human breast cancer cells in vitro." (PMID 37581480, 2023). "In human breast cancer cells, the high expression of TRPC5, and consequently, the high Ca2+ influx via the channel activated the transcription factor NFATC3 (Nuclear Factor of Activated T Cells, Cytoplasmic 3), which triggers p-gp transcription." (PMID 37755210, 2023). "Other notable genes decreased by SK1 KD were NDUFA2 in prostate and E2F5, NAGK, VAPB, NFATC3, CDK2 in breast cancer cell lines." (PMID 30971929, 2019). "This demonstrates that NFATc3 is required for SFRP2 induced tube formation, and tacrolimus inhibits angiogenesis in vitro and breast carcinoma growth in vivo." (PMID 21673995, 2011). "In a similar study in a mouse model of breast cancer, hesperidin was reported to suppress VEGF production and tumour growth and to reduce microvessel density through suppressing the expression of VEGF, VEGFR2 and NFATc3 proteins." (PMID 37581480, 2023).